SLCO1B1 (solute carrier organic anion transporter family member 1B1)
Diseases named in the same sentence as SLCO1B1 in open-access papers (continued):
Sharing a sentence is not in itself a finding about the gene and the disease.
cerebral infarction (1 paper, 2020). An ischemic condition of the brain, producing a persistent focal neurological deficit in the area of distribution of the cerebral arteries. "This is the first study about the relationship of cerebral infarction and SLCO1B1 gene polymorphism." (PMID 32891149, 2020). "In addition, no information has been published about relationship between cerebral infarction and SLCO1B1 gene polymorphisms in other populations." (PMID 32891149, 2020). "However, the relationship between genetic polymorphisms of APOE and SLCO1B1 and cerebral infarction (CI) remains unclear." (PMID 32891149, 2020).
depression (1 paper, 2019). "The risk of moderate-severe depression was highest among carriers of the minor G allele of SLCO1B1 rs4149056 who received chemotherapy only (p = 0.002)." (PMID 31181069, 2019). "Moreover, we identified the association between depression and the presence of variant rs4149056 in SLCO1B1 gene." (PMID 31181069, 2019).
endometrial cancer (1 paper, 2025). Primary or metastatic malignant neoplasm involving the endometrium (mucous membrane that lines the endometrial cavity). "In this study, we identified two SNPs, rs17601876 in CYP19A1 and rs2900478 in SLCO1B1, that were associated with endometrial cancer." (PMID 40141105, 2025). "Using the chi-square test to compare carrier proportions between the case and control groups, we found that rs2900478 in SLCO1B1 and rs17601876 in CYP19A2 displayed significantly different distributions, indicating a potential association with endometrial cancer." (PMID 40141105, 2025).
Graves disease (1 paper, 2022). Graves' disease is an autoimmune disorder that leads to overactivity of the thyroid gland (hyperthyroidism).It is caused by an abnormal immune system response that causes the thyroid gland to produce too much thyroid hormones. "Polymorphisms of SLCO1B1 have also been associated with the occurrence of methimazole-induced liver injury in patients with Grave’s disease." (PMID 35053465, 2022).
hereditary hemochromatosis (1 paper, 2019). An inherited metabolic disorder characterized by iron accumulation in the tissues. "Unlike several other hereditary liver metabolic diseases, such as Wilson disease and hereditary hemochromatosis, the hotspots for SLCO1B1 and SLCO1B3 mutations are quite similar between different populations." (PMID 32082363, 2019).
Hyperglycemia (1 paper, 2022). An increased concentration of glucose in the blood. "First, we investigated the possibility that SLCO1B1 rs4149056 has a direct effect on the risk of T2D and hyperglycemia." (PMID 36557197, 2022).
hyperlipidemia (1 paper, 2021). "Over a 4-month period, the present study determined the T521C genotype frequency and the dynamics of total cholesterol and LDL cholesterol in patients with hyperlipidemia carrying the SLCO1B1 C521T and MDR1 C3435T polymorphisms." (PMID 34749751, 2021).
hypogonadism (1 paper, 2025). A disorder characterized by decreased function of the gonads. "Protein-coding variants in several liver genes, such as PNPLA3, GCKR, SLCO1B1, SERPINA1, HGFAC, and UGT2B15, were significantly associated with total testosterone levels and hypogonadism risk." (PMID 40316537, 2025).
kidney transplant (1 paper, 2022). A surgical procedure in which one or both kidneys from a donor are implanted into a recipient. "Moreover, a Chinese study investigated the associations between tacrolimus concentrations and SLCO1B1 polymorphisms in kidney transplant recipients, showing that TAC-dose-adjusted concentration was considerably higher in SLCO1B1 rs2306283 CC carriers compared with CT and TT carriers." (PMID 35892699, 2022).
Liver toxicity (1 paper, 2014). "Liver toxicity was significantly less frequent in carriers of polymorphic SLCO1B1 rs11045879 (p = 0.014; OR = 0.18; 95% CI = 0.05−0.71) and rs4149056 (p = 0.028; OR = 0.23; 95% CI = 0.06−0.85) alleles." (PMID 24991206, 2014).
malaria (1 paper, 2017). Malaria is a serious and sometimes fatal disease caused by a parasite that commonly infects a certain type of mosquito which feeds on humans. "In the present study, the SLCO1B1*14 allele carriers have lower gametocytemia clearance rate over treatment time in malaria." (PMID 28975866, 2017).
multiple myeloma (1 paper, 2023). "In this study, the A388G single nucleotide polymorphism in the SLCO1B1 gene in Polish multiple myeloma patients was determined." (PMID 36478296, 2023). "Therefore, study aimed to assess the potential impact of the one of most common functional A388G SNP variants in SLCO1B1 gene on the risk of multiple myeloma development and clinical outcomes." (PMID 36478296, 2023). "Our work aimed to determine SLCO1B1 A388G gene polymorphism in multiple myeloma patients." (PMID 36478296, 2023). "Our study showed that SNP A388G of the SLCO1B1 gene does not predispose to an increased individual risk of developing multiple myeloma and does not affect the values of selected clinical parameters." (PMID 36478296, 2023).
Nausea (1 paper, 2021). A sensation of unease in the stomach together with an urge to vomit. "The objective for this study was to investigate whether MTX-induced nausea was associated with selected SNPs in candidate genes encoding MTX transporter proteins (SLCO1B1, SLCO1B3, SLC19A1, ABCB1, ABCC2), the MTHFR enzyme (MTHFR) and the 5-HT3-receptor (HTR3A, HTR3B), in children with JIA." (PMID 33794950, 2021).
non-Hodgkin lymphoma (1 paper, 2021). Distinct from Hodgkin lymphoma both morphologically and biologically, non-Hodgkin lymphoma (NHL) is characterized by the absence of Reed-Sternberg cells, can occur at any age, and usually presents as a localized or generalized lymphadenopathy associated with fever and weight loss. "SLCO1B1 rs4149056 genetic polymorphism could predict methotrexate hepatotoxicity in Chinese patients with non-Hodgkin lymphoma." (PMID 33386894, 2021).
osteoarthritis (1 paper, 2022). A noninflammatory degenerative joint disease occurring chiefly in older persons, characterized by degeneration of the articular cartilage, hypertrophy of bone at the margins and changes in the synovial membrane. "In addition to changes in UGT1A1, polymorphisms in the transporter proteins SLCO1B1 and ABCB1 have been reported to influence the response of osteoarthritis patients to raloxifene treatment." (PMID 35453603, 2022).
parasitemia (1 paper, 2017). "SLCO1A2 and SLCO1B1 genes were associated with the gametocytemia clearance rate over treatment time in GEE analyses adjusted for age, gender, co-medication, parasitemia baseline level, CYP2C8 genotypes and genetic ancestry." (PMID 28975866, 2017).
psoriasis (1 paper, 2018). An autoimmune condition characterized by red, well-delineated plaques with silvery scales that are usually on the extensor surfaces and scalp. "The SLCO1B1 rs4149056 and SLC22A1 rs2282143 polymorphisms affect the clinical efficacy of acitretin in the treatment of psoriasis." (PMID 30181619, 2018).
psychotic disorder (1 paper, 2023). An abnormal condition of the mind that involves a loss of contact with reality. "We explored the effect of six rare SLCO1B1 single nucleotide variants (SNVs) occurring in Finnishindividuals with a psychotic disorder on expression and functionalityof the OATP1B1 protein." (PMID 36779498, 2023).
pulmonary fibrosis (1 paper, 2023). Chronic progressive interstitial lung disorder characterized by the replacement of the lung tissue by connective tissue, leading to progressive dyspnea, respiratory failure, or right heart failure. "Additionally, in patients recieving AZA, SLCO1B1 rs4149056 minor allele was protective against pulmonary fibrosis (p = 0.04), however this signal was completely lost after adjusting for confunding factors (padj = 0.12)." (PMID 37239884, 2023).
senile cataract (1 paper, 2023). A cataract with no obvious cause occurring in persons over 50 years old. "Among statin users, the SLCO1B1*5 genotype is associated with a 30% risk reduction of non-senile cataracts." (PMID 37221222, 2023). "We hereby demonstrate on a large cohort that the SLCO1B1*5 genotype, known to lead to increased statin exposure, is significantly associated with decreased risk of non-senile cataracts in those taking statins." (PMID 37221222, 2023).
Tetralogy of Fallot (1 paper, 2024). A congenital cardiac malformation comprising pulmonary stenosis, overriding aorta, ventricular septum defect, and right ventricular hypertrophy. "The results showed that high PM2.5 could increase the risk of tetralogy of Fallot by mutating the SLCO1B1 fragment gene." (PMID 39135922, 2024).
vitamin D deficiency (1 paper, 2026). A nutritional condition produced by a deficiency of VITAMIN D in the diet, insufficient production of vitamin D in the skin, inadequate absorption of vitamin D from the diet, or abnormal conversion of vitamin D to its bioactive metabolites. "The SLCO1B1 c.521T>C polymorphism affects hepatic statin transport, while vitamin D deficiency may influence lipid metabolism and muscular tolerance." (PMID 41595648, 2026). "The SLCO1B1 c.521T>C variant primarily affected safety rather than efficacy, while severe vitamin D deficiency might contribute to diminished statin response." (PMID 41595648, 2026).
myopathy (121 papers, 2009 to 2026). A disease of the muscle in which the muscle fibers do not function properly. "SLCO1B1 is a major gene for statin intolerance and increasing number of variants have been connected to side effects like myopathy." (PMID 39802654, 2025). "In 2008, data from a big genome-wide study showed a strong association between a SLCO1B1 variant (rs4149056) and an increased risk of statin-induced myopathy." (PMID 38523294, 2024). "One genome‐wide analysis conducted on patients receiving statin therapy identified a polymorphism in the SLCO1B1 gene, encoding a protein responsible for the hepatic uptake of statins, which was associated with an increased risk of myopathy." (PMID 38711272, 2024). "For example, heterozygotes for SLCO1B1*5 have a moderate risk whereas homozygotes (*5/*5) are at high risk for myopathies if treated with simvastatin." (PMID 38020121, 2023). "For example, the single nucleotide polymorphism (c.521T > C, p.Val174Ala) in the SLCO1B1 gene reduces the transport capacity of OATP1B1, leading to elevated plasma levels of simvastatin acid and elevating the risk of simvastatin-induced myopathy." (PMID 37624085, 2023). "SLCO1B1 genetic variants, in particular the rs4149056C allele, have been associated with higher risk of myopathy in simvastatin treated patients." (PMID 37111771, 2023). "Statins are transported into the liver by the organic anion transporting polypeptide 1B1 (OATP1B1) encoded by SLCO1B1, which controls the systemic exposure of many statins and is associated with statin-induced myopathy." (PMID 37818163, 2023). "SLCO1B1 was most extensively investigated among Asian populations due to its strong association with statin-induced myopathy among Caucasians as reported in the STRENGTH and SEARCH trials." (PMID 37818163, 2023). "The mechanism of SLCO1B1*5 variant causing statin-related myopathy is through the accumulation of circulating simvastatin acid (the active form of simvastatin) reflecting liver transport." (PMID 38550953, 2023). "The Statin Response Examined by Genetic Haplotype Markers (STRENGTH) study stated that the several variants in the SLCO1B1 gene, which encodes OATP1B1, affect the hepatic uptake of statins leading to myopathy." (PMID 37206522, 2023). "On the other hand, a recent Malaysian study reported that SLCO1B1 T89595C (rs4363657) polymorphism was a significant risk factor for statin-induced myopathy in heterozygote carriers compared to wild-type and variant homozygotes." (PMID 37818163, 2023). "Rs4149056 (SLCO1B1*5) is a functional polymorphism in exon 5 and a well-studied SNP associated with drug toxicities such as stain-induced myopathy and methotrexate toxicity." (PMID 37749323, 2023). "The SLCO1B1 c.521T>C SNP has been strongly linked to the development of myopathy in individuals taking simvastatin." (PMID 38003001, 2023). "For statins, 31.5% of patients carried at least one allele at the genotyped SLCO1B1 variant (rs4149056), increasing their risk of developing myopathy." (PMID 36154845, 2022). "SLCO1B1 c.521T>C (rs4149056) has been verified to be related to statin-induced myopathy risk, which is widely used to guide dose determination of statin drugs such as atorvastatin, pitavastatin, and simvastatin." (PMID 36601065, 2022). "Polymorphisms of the SLCO1B1 gene are the best-known pharmacokinetic changes in statin-associated myopathy." (PMID 35955495, 2022). "A coding variant (p.Val174Ala, rs4149056) in the SLCO1B1 gene was found to be significantly associated with myopathy, making this the most validated genetic basis for SAMS." (PMID 35955495, 2022). "The 1B1*15 haplotype, which includes SLCO1B1*5 (rs4149056, 521T > C) and SLCO1B1*1B (rs2306283, 388 A > G), has been identified as a risk factor for myopathy caused by multiple statins (n = 7); lipid-lowering agents." (PMID 36388934, 2022). "In the previously discussed association between SLCO1B1 and statin-induced myopathy, the variant originally identified by the GWAS was intronic." (PMID 35373152, 2022).
myopathy (continued). "There is solid evidence that rs4149056 (c.521T>C), which is part of the SLCO1B1*5, SLCO1B1*15, and SLCO1B1*17 alleles, is a decreased-function variant that predisposes to simvastatin-induced myopathy." (PMID 35631530, 2022). "It is well-studied that genetic variation of c.521T>C in SLCO1B1 is a genetic risk factor for statin myopathy." (PMID 36601065, 2022). "Further study reported a significant association between patients carried SLCO1B1 T521C and myopathy induced by statins, including simvastatin, rosuvastatin and ceruvastatin." (PMID 35548363, 2022). "The patients with heterozygous and homozygous carriers of the C allele at rs4149056 (*5) in SLCO1B1 had a significantly increased risk for myopathy, compared with the patients with TT homozygotes, when taking statins." (PMID 36601065, 2022). "For statins, 50 participants (31.25%) carried at least one allele at the genotyped SLCO1B1 variant, increasing their risk of developing myopathy." (PMID 36154845, 2022). "The Dutch Pharmacogenetics Working Group (DPWG) recommends an alternative agent to atorvastatin and simvastatin or a dose adjustment depending on other risk factors for statin-induced myopathy in SLCO1B1 rs4149056 CC or TC carriers." (PMID 33805706, 2021). "The hepatic uptake of simvastatin is mediated by the organic anionic transporter SLCO1B1 and associations between lower activity SLCO1B1 allelic variants and simvastatin myopathy has been observed." (PMID 34834577, 2021). "A previous study on SLCO1B1 reported an 18% cumulative risk of simvastatin-induced myopathy for the CC genotype (frequency in HK: 1.92%) and a 3% cumulative risk for the CT genotype (frequency in HK: 23.89%)." (PMID 33600428, 2021). "Patients with statin-induced myopathy can be classified into three risk groups according to their SLCO1B1 genotype." (PMID 34749751, 2021). "This meta-analysis was conducted to determine the genotypic effects of rs4149056 and rs2306283 polymorphism in SLCO1B1 gene on myopathy in patients with statin." (PMID 33608664, 2021). "Recently, five meta-analyses (MA), which included individual studies upto 2017, investigated the association between SLCO1B1 gene and myopathy in statin users." (PMID 33608664, 2021). "The use of an alternative statin (e.g., fluvastatin) is recommended for patients with SLCO1B1 rs4149056 T>C, C/C (*5/*5) or T/C (*1/*5) genotypes and additional significant risk factors for statin-induced myopathy." (PMID 33805706, 2021). "This meta-analysis of genetic association studies was conducted to assess the genetic effects of single nucleotide polymorphisms (rs4149056 and rs2306283) of the SLCO1B1 gene on myopathy." (PMID 33608664, 2021). "The relationship between this transporter and the pharmacokinetics of statins is so relevant that it has been established that SLCO1B1 is one of the risk predictors of myopathy caused by statins." (PMID 34867363, 2021). "Some studies showed that SLCO1B1 genetic variants are strongly associated with statin-induced myopathy." (PMID 33027917, 2020). "SLCO1B1*5 has been strongly associated with myopathy among the simvastatin users with an odds ratio (OR) ranging from 4.5 in heterozygotes to 16.9 in homozygotes." (PMID 32581780, 2020). "Overall, 120 participants (29%) had a SLCO1B1 genotype indicating increased simvastatin myopathy risk (T/C or C/C genotype)." (PMID 33270123, 2020). "The PharmGKB database assesses the evidence as level A (highest level evidence) that statins cause myopathy in patients with gene SLCO1B1 allele variants." (PMID 32796505, 2020). "Overall, 120 participants (29%) had a SLCO1B1 genotype indicating increased simvastatin myopathy risk." (PMID 33270123, 2020). "The solute carrier organic anion transporter family member 1B1 (SLCO1B1) genotype is associated with simvastatin myopathy risk and is proposed for clinical implementation." (PMID 33270123, 2020).